TGFBR1 (transforming growth factor beta receptor 1)
Diseases named in the same sentence as TGFBR1 in open-access papers (continued):
Sharing a sentence is not in itself a finding about the gene and the disease.
gastric cancer (23 papers, 2009 to 2025). A primary or metastatic malignant neoplasm involving the stomach. "This case–control study combined retrospective study observed that two polymorphisms (rs334348, rs10512263) in TGFBR1 were associated with risk of gastric cancer, and that rs1927911and rs10512263 were associated with survival of gastric cancer patients." (PMID 30479570, 2018). "We concluded that two polymorphisms (rs334348, rs10512263) in TGF-BR1 were associated with risk of gastric cancer, and that TLR4 rs1927911 and TGFBR1 rs10512263 were associated with clinical outcomes of gastric cancer patients." (PMID 30479570, 2018). "In the retrospective study, we observed TLR4 rs1927911 and TGFBR1 rs10512263 were associated with clinical outcomes of gastric cancer patients." (PMID 30479570, 2018). "TGFBR1 was associated with poor survival in patients with gastric cancer." (PMID 34790582, 2021). "Two polymorphisms in TGFBR1 were observed to be potentially associated with risk of gastric cancer." (PMID 30479570, 2018). "Moreover, serum TGF-β1 levels implicating a predictive and prognostic value for patients with gastric cancer may indicate polymorphisms in genes of TGF-β1 pathway including TGFBR1 could influence the risk and clinical progression of gastric cancer." (PMID 30479570, 2018). "CircRNA CircCACTIN promotes gastric cancer progression by sponging MiR-331-3p and regulating TGFBR1 expression." (PMID 38459596, 2024). "As the main mediator of immune-related processes, TGFBR1 can be a potential predictor for survival in patients with gastric cancer." (PMID 36676763, 2023). "In short, we concluded that two polymorphisms (rs334348, rs10512263) in TGFBR1 were associated with risk of gastric cancer, and that TLR4 rs1927911 and TGFBR1 rs10512263 were associated with clinical outcomes of gastric cancer patients." (PMID 30479570, 2018). "Here, we conducted a case–control study to assess the susceptibility of polymorphisms in IL-16, TGFBR1 and TLR4 to risk of gastric cancer in a Chinese population, and the prognostic value of the polymorphisms was also evaluated by a retrospective study." (PMID 30479570, 2018). "Furthermore, these results underscore the potential of TGFBR1 as both a prognostic biomarker and a therapeutic target, warranting further investigation in aggressive forms of gastric cancer." (PMID 41373412, 2025). "In addition, the expression profile of gastric cancer is elevated in conjunction with an increase in the number of abnormally proliferating gastric epithelial cells, and TGFBR1 is also elevated." (PMID 39364054, 2024). "Moreover, this study observed TGFBR1 rs10512263 has a predictive value for clinical outcomes of gastric cancer patients." (PMID 30479570, 2018). "This is a study firstly discussed the relation of polymorphisms in genes of IL-16, TGFBR1 and TLR4 pathways and survival time of gastric cancer patients in Chinese population and our study could provide epidemiology data for further study." (PMID 30479570, 2018). "Therefore, targeting TGF-β signaling pathway via the TGFBR1 may be an effective therapeutic strategy for the inhibition of gastric cancer metastasis." (PMID 39364054, 2024). "We found that DCLK1 expression significantly correlates with both TGFB1 and CXCL12 and their receptors TGFBR1, TGFBR2, and TGFBR3, and CXCR4, respectively, in colon and stomach cancer patients." (PMID 31979136, 2020). "To investigate the susceptibility and prognostic value of genetic variations of IL-16, TGFBR1 and TLR4 pathways to gastric cancer, we performed a case–control study combined a retrospective study in a Chinese population." (PMID 30479570, 2018). "Notably, in gastric cancer (GC), the overexpression of TGF-β and its receptor TGFBR1 serve as indicators of poor prognosis, especially for patients with high-grade tumors (grade 3)." (PMID 41373412, 2025).
gastric cancer (continued). "Finally, we verified that TGFB1I1, TGFBR1, SMAD9 and SMAD4 are low expressed in gastric cancer by immunohistochemistry at the protein level, and RCAN2 is also low expressed in gastric cancer." (PMID 36483555, 2022).
melanoma (17 papers, 2013 to 2025). A malignant, usually aggressive tumor composed of atypical, neoplastic melanocytes. "The inhibition of glioblastoma cancer initiating (stem) cells by TGFBR1 inhibitors is consistent with our data, and provides support for our conclusion that TGFBR1 activity is required for melanoma stem-cell like properties." (PMID 27835901, 2016). "So far, our data implicate autocrine TGFβ signalling through TGFBR1 as a critical factor in melanoma clonogenicity and tumour formation, however, it was important to rule out off-target effects of the inhibitor." (PMID 27835901, 2016). "Pharmacological inhibition of the TGFBR1 blocked the clonogenicity of human mutant BRAF melanoma cells through SMAD4-independent inhibition of mitosis, and also inhibited metastasis in xenografted zebrafish." (PMID 27835901, 2016). "In this study, we now provide evidence that melanoma cells are “hard-wired” to depend on autocrine TGFβ signalling through TGFBR1 for tumour establishment and clonogenicity." (PMID 27835901, 2016). "Although the SMAD-dependent induction of RHO GEFs has been described in other studies, how TGFBR1 directly activates RHOA in melanoma cells in a SMAD-independent manner is unclear at present." (PMID 27835901, 2016). "The addiction of mutant BRAF melanoma cells to signalling through TGFBR1 suggests a potential novel therapeutic approach for mutant BRAF-driven cancers." (PMID 27835901, 2016). "So far, our murine xenograft assays, and inhibition of clonogenic potential of melanoma cells in low cell density 3D and 2D culture systems, suggest that TGFBR1 inhibitors would be effective in preventing establishment of disease." (PMID 27835901, 2016). "TGFBR1 inhibitors block the enhanced proliferation of paradoxically activated PLX-4720 treated melanoma cells, and can be used to effectively inhibit metastatic melanoma in a zebrafish xenograft model." (PMID 27835901, 2016). "Colony formation and cell proliferation decreased following TGFBR1 knockdown, confirming that TGFBR1 is required for melanoma colony formation." (PMID 27835901, 2016). "Our data overall suggest that TGFBR1 inhibitors would reduce the metastatic burden in BRAF mutant melanoma by preventing invasion and/or outgrowth of metastatic colonies." (PMID 27835901, 2016). "In addition, inhibitors of the TGFβ receptor TGFBR1 prevented the development of resistance to BRAF inhibitor vemurafenib in BRAF mutant melanoma cells." (PMID 36295658, 2022). "Nevertheless, the dependence of melanoma cells on TGFBR1 for clonogenicity suggests that TGFBR1 inhibitors could be effective in preventing spread or outgrowth of micrometastases." (PMID 27835901, 2016). "We found that autocrine TGFβ signalling through TGFBR1 is an intrinsic requirement for the clonogenic potential of mutant BRAF transformed cells, indicating that mutation of BRAF may be useful as a biomarker for TGFβ tumour promoting activity in melanoma." (PMID 27835901, 2016). "When investigating the therapeutic potential of combining inhibitors of mutant BRAF and TGFBR1, we noted that unexpectedly, low-dose PLX-4720 (a vemurafenib analogue) promoted proliferation of drug-naïve melanoma cells." (PMID 27835901, 2016). "On the other hand, the top downregulated genes formed 4 subgroups and were related to melanogenesis (Wnt5a, Mitf, Pomc, Mc1r, Kit), melanoma (Fgf9, Fgf12, Fgf2), MAPK signaling pathway (Ncam1, Prkcb, Map3k4, Pla2g4a, Mapk14, Mapk11), and aging (Tgfbr1, Il6, Nox4)." (PMID 36555664, 2022). "In addition, circ_0002770 contributed to the progression of melanoma via interacting with miR-331-3p and elevating DUSP5/TGFBR1 expression." (PMID 34056112, 2021). "We showed that although melanoma cells rely on TGFBR1 kinase activity, they do not require SMAD4 for either colony formation, or for the response to TGFBR1 inhibition." (PMID 27835901, 2016).
aortic aneurysm (15 papers, 2013 to 2023). A ruptured aneurysm located in the wall of the proximal portion of the descending aorta proceeding from the arch of the aorta. "Mutations in TGFBR1 have been associated with aortic aneurysms, as well as impaired connective tissues leading to joint laxity." (PMID 31783652, 2019). "We have recently reported that the ablation of SMC-specific TGFBR1 causes aortic aneurysms and dissections." (PMID 27739498, 2016). "Since TGFBR1 mutations were first described in patients with MSSE, two patients with MSSE and aortic aneurysms have been described." (PMID 33256177, 2020). "Additionally, mutation of TGF-β signal pathway components such as TGFBR1 and TGFBR2 is directly involved in the progression of the aortic aneurysm." (PMID 33788038, 2021). "Recently, a missense mutation in transforming growth factor-beta receptor 2 gene (TGFBR2) was found in a patient with BAV and aortic aneurysm, but earlier studies found no mutation in either TGFBR1 or TGFBR2 in patients with familial and sporadic BAV disease." (PMID 23578328, 2013). "Regarding to TGFBR1 and TGFBR2 genes, in contrast with a recent paper showing a missense mutation in TGFBR2 gene in a patient with BAV and aortic aneurysm, our findings support the studies suggesting that mutations in these genes are rarely identified in patients with familial BAV." (PMID 23578328, 2013).
non-small cell lung carcinoma (15 papers, 2007 to 2025). A group of at least three distinct histological types of lung cancer, including non-small cell squamous cell carcinoma, adenocarcinoma, and large cell carcinoma. "For example, upregulation of TGFBR1 transcript enhanced the proliferation, invasion, and migration ability of non-small-cell lung cancer cells." (PMID 40166052, 2025). "LncRNA RMRP recruits YBX1 to upregulate the transcription of TGFBR1, thereby promoting the proliferation and progression of non-small cell lung cancer." (PMID 38491348, 2024). "In non-small cell lung cancer, the overexpression of miR-3607 in tumor cells could inhibit cell proliferation, migration, invasion and cell cycle by downregulating TGFBR1 and CCNE2." (PMID 32404179, 2020). "The stability of lncRNA RMRP is enhanced through m6A modification, regulating the TGFBR1/SMAD2/SMAD3 pathway and the proliferation and progression of non-small cell lung cancer." (PMID 35585970, 2022). "To illustrate, in non-small cell lung cancer, METTL3-mediated m6A modification could enhance the stability of methylated lncRNA-RMRP transcripts, which further promotes TGFBR1 transcription and the activation of TGFBR1/SMAD2/SMAD3 signaling pathway." (PMID 40089501, 2025). "RMRP is upregulated in non-small cell lung cancer (NSCLC) and promotes proliferation, invasion, and migration by interacting and recruiting YBX1 to the TGF-β receptor 1 (TGFBR1) promoter, upregulating TGFBR1 and enhancing the TGFBR1/SMAD2/SMAD3 growth signaling pathway." (PMID 36754845, 2023).
colon cancer (13 papers, 2004 to 2022). "Recent studies suggest that the association of the TGFBR1*6A allele with colon cancer is either weak (OR: 1.2; 95% CI: 1.01–1.43) or of borderline significance (OR: 1.13; 95% CI: 0.98–1.30)." (PMID 19538729, 2009). "The TGFBR1*6A allele was more prevalent among colon tumour patients than among rectal tumour patients." (PMID 19538729, 2009). "No data are available regarding the risk of colon versus rectal cancer for the TGFBR1*6A allele because data from colorectal and colon cancer studies were pooled in the meta-analyses." (PMID 19538729, 2009). "We found that the immunomodulator TGFBR1 showed positive correlation with TPM1 expression in colon cancer, and the immunomodulator TNFRSF25 showed negative correlation with TPM1." (PMID 34180352, 2021). "This was similar to the 66% with primary colon cancer in patients with normal TGFBR1 allelic expression (p = 0.507; Fisher's Exact Test)." (PMID 20500843, 2010). "Fifty-five percent of the patients with decreased TGFBR1 allelic expression had a primary colon cancer." (PMID 20500843, 2010). "We have previously shown that TGFBR1*6A homozygotes have an O.R of 2.69 and 2.02 for ovarian and colon cancer, respectively." (PMID 15385056, 2004). "As we proved here by several methods, TGFBR1 is a functional downstream target of miR-4666-3p, and alterations in miR-4666-3p and TGFBR1 expression could affect the stemness of colon cancer cells and activation of TGF-β/Smad pathway." (PMID 31824844, 2019). "Knockdown of CEA in colon cancer DLD1 cells increased TGFBR1 protein stability, suggesting that CEA may regulate TGFBR1 levels post-transcriptionally." (PMID 27100181, 2016). "Moreover, when only colon cancer cases where considered, there was a difference of borderline significance for TGFBR1*6A carriers (p = 0.071) with an OR = 1.47 (95% CI: 0.979–2.203)." (PMID 19538729, 2009). "Small molecule inhibitors for both TGFBR1/2 and ACVR1B are available and conceivably could be used as adjuvant therapies in advanced colon cancer, but biomarkers to determine treatment suitability and specifically to avoid augmentation of oncogenic signaling are lacking." (PMID 26497569, 2015).
glioblastoma (13 papers, 2015 to 2025). The most malignant astrocytic tumor (WHO grade IV). "Deregulated TGFBR1 is tightly associated with glioblastoma progression." (PMID 34225723, 2021). "Intriguingly, the in vivo effect of humanin on glioblastoma was significantly reduced by the treatment of TGFBR1 inhibitor." (PMID 38942749, 2024). "In this study, we identified that Tim-1 was abnormally elevated in glioblastoma, and its knockdown inhibited glioblastoma cell proliferation, invasion, and migration via the miR-133a/TGFBR1 axis and the Wnt/β-catenin pathway activation." (PMID 34225723, 2021). "We also showed that miRNAscontribute to regulating the AKT and TGFB signalling pathway by targeting theAKT2 and TGFBR1 genes in glioblastoma tissues." (PMID 34455717, 2021). "Briefly, we proved that Tim-1 knockdown suppressed the Wnt/β-catenin pathway activation via the miR-133a/TGFBR1 axis in glioblastoma, and it promise to be a potential drug target in clinical practice." (PMID 34225723, 2021). "CCK-8 detection, Transwell assay, and wound healing test were used to verify the effect of upregulated miR-133a combined with the upregulation of TGFBR1 on glioblastoma cells." (PMID 34225723, 2021). "Tim-1 knockdown inhibited glioblastoma cell proliferation, invasion, and migration through the miR-133a/TGFBR1 axis and restrained the activation of the Wnt/β-catenin pathway." (PMID 34225723, 2021). "In conclusion, this study supported that Tim-1 knockdown inhibited glioblastoma cell biological behaviors and the Wnt/β-catenin pathway activation via regulating the miR-133a/TGFBR1 axis." (PMID 34225723, 2021). "qRT-PCR results revealed that miR-133a expression in glioblastoma was clearly decreased, with the increased expression of TGFBR1." (PMID 34225723, 2021). "In this study, we identified that Tim-1 participated in the pathogenesis of glioblastoma via regulating the miR-133a/TGFBR1 axis." (PMID 34225723, 2021). "Subsequently, we elevated miR-133a expression with miR-133p mimic, and the changes of TGFBR1 expression were detected in glioblastoma cells U87 and U251 using qRT-PCR and WB." (PMID 34225723, 2021). "Blocking the Tim-1/miR-133a/TGFBR1 axis might develop as a novel robust therapeutic approach for glioblastoma treatment." (PMID 34225723, 2021). "Taken together, silencing Tim-1 could inhibit glioblastoma cell growth via regulating the miR-133a/TGFBR1 axis." (PMID 34225723, 2021). "Studies have also reported that EZH2 is involved in a novel miR-490-3p/TGIF2/TGFBR1 axis inducing migration and EMT in glioblastomas." (PMID 36230759, 2022).
Myocardial fibrosis (13 papers, 2021 to 2026). "In cardiac diseases, TGFBR1 is mainly involved in myocardial fibrosis, and inhibition of its expression can reduce collagen deposition and improve cardiac function through the Smad signaling pathway." (PMID 40880411, 2025). "Inhibition of TGFBR1 signaling pathway reduced myocardial fibrosis and cardiac dysfunction in mice, and improved cardiac function in mice with myocardial infarction." (PMID 40166052, 2025). "We found that systemic inhibition of miR-181c-5p attenuated the development of myocardial fibrosis in a rodent model of mild diastolic dysfunction, in part by modulating Tgfbr1-signaling." (PMID 38725830, 2024). "TMAO can increase the expression of TGFB receptor I (TGFBR1), activate the TGFBR1/Smad2 pathway, and aggravate myocardial fibrosis in mice." (PMID 34925503, 2021). "Additionally, Masson’s trichrome staining demonstrated an increase in the area of myocardial fibrosis in the left ventricle of HFpEF group compared with the control group, with TGFBR1 gene silencing leading to a reduction in myocardial fibrosis in HFpEF mice." (PMID 40880411, 2025). "Silencing TGFBR1 attenuates myocardial fibrosis, while it is unknown whether it inhibits cardiac hypertrophy." (PMID 40880411, 2025). "Therefore, curcumin and resveratrol have great potential to improve AF by acting on TGFBR1 expression to reduce myocardial fibrosis." (PMID 36246656, 2022). "Finally, TGFBR1 was found to dock well with curcumin and resveratrol, and it was further verified that curcumin and resveratrol could significantly reduce myocardial fibrosis." (PMID 36246656, 2022). "Silencing TGFBR1 inhibited this activation, reduced the expression of collagen I and collagen III, and ameliorated myocardial fibrosis in HFpEF mice." (PMID 40880411, 2025).
ovarian carcinoma (13 papers, 2004 to 2024). A malignant neoplasm originating from the surface ovarian epithelium. "Two recent meta-analyses show that TGFBR1*6A carriers may have an increased risk of breast, colon and ovarian cancer." (PMID 15385056, 2004). "TGFBR1*6A, a common hypomorphic variant of the type I Transforming Growth Factor Beta receptor, is emerging as a tumor susceptibility allele that predisposes to the development of breast, colon and ovarian cancer." (PMID 15385056, 2004). "Around 30% of patients with ovarian cancer bear a dinucleotide insertion in exon 5 of the Tgfbr1 gene." (PMID 17705854, 2007). "In this regard, the present work found a decrease in TGFBR1 protein levels in ovarian cancer tissue, thus suggesting that DHT might downregulate TGFBR1 protein levels but not the mRNA levels of this receptor." (PMID 26091707, 2016). "TGFB1 and TGFBR1 expression did not affect survival (data not shown), while TGFB2, TGFB3, TGFBR2, and TGBR3 overexpression decreased patient survival among ovarian cancer patients when the microarray data was assessed." (PMID 38196068, 2024).